DUSP22 (dual specificity phosphatase 22)
Diseases named in the same sentence as DUSP22 in open-access papers (continued):
Sharing a sentence is not in itself a finding about the gene and the disease.
tumor (16 papers, 2011 to 2025). "In the Long-Read POG cohort, 63.11% of tumor samples with ASE in DUSP22 showed allele-specific promoter methylation in trans and 81.15% showed allele-specific gene body methylation in cis with the major expressed allele." (PMID 39406235, 2024). "Further searching for a second hit, we analyzed tumor DNA samples for DUSP22 mutations in the promixal promoter, exons and splice sites." (PMID 27626696, 2016). "As for other tumor suppressors whose inactivation is a secondary event, loss of DUSP22 function may thus only contribute to transformation in cells already carrying other initiating oncogenic events." (PMID 27626696, 2016). "Additionally, low expression of DUSP22 was significantly associated with various clinicopathological parameters, such as tumor stage, TNM cancer stage, and tumor grade, suggesting that decreased DUSP22 expression could be a key factor in the initiation and advancement of LUAD." (PMID 38877005, 2024). "In this study, we showed that DUSP22 expression was significantly reduced in LUAD tissues compared to non-tumor tissues." (PMID 38877005, 2024). "This epigenome-wide association analysis revealed a differentially methylated region (DMR) in the promoter region of DUSP22, a protein phosphatase and known tumor suppressor, in response to total and food periconceptional folate intake." (PMID 36831356, 2023). "DUSP22 is widely expressed in various different types of tissues and cells, thus mediating diverse pathophysiological processes, such as cell motility, tumor progression, and inflammation." (PMID 36209205, 2022). "Using the zebrafish model of tumor cell dissemination, it was also confirmed that in vivo treatment with a small molecule inhibitor of DUSP22 blocked the metastasis of cancer cells in the early stage." (PMID 34207247, 2021). "Altogether, our study supports a tumor suppressor function of DUSP22 and that its inactivation contributes to the development of PTCL." (PMID 27626696, 2016). "Functional studies were thus performed with the 205 amino-acids isoform to investigate the potential tumor suppressor role of DUSP22 in T-cells." (PMID 27626696, 2016). "Altogether, our study shows that inactivation of DUSP22 contributes to T cell transformation and supports a tumor suppressor function of DUSP22." (PMID 27626696, 2016). "Otherwise, little is known about the role of DUSP22 in physiologic and pathologic pathways; evidence suggests it may function as a tumor suppressor in neoplasia." (PMID 39221352, 2024). "Additionally, HCC cell lines (Hep3B, HepG2, and SMMC-7721) also exerted significantly decreased DUSP22 expression compared to the non-tumor cell line." (PMID 36209205, 2022). "DUSP22 can regulate MAPK signal transduction and is expressed in various types of tissues and cells, demonstrating that DUSP22 may regulate several crucial biological events, such as inflammatory response and tumor cell proliferation." (PMID 36209205, 2022). "Cell 3 and its primary tumor 3 presented 28 genomic alterations in common, including gains of 4q12 (PDGFRA), an amplification of 11p15.5 (H19 and IGF2 genes), and a loss of 6p25.3 (DUSP22)." (PMID 33917394, 2021). "Our goal was thus to investigate the expression status of DUSP22 isoforms in normal lymphocytes and PTCL, the mechanism of second allele silencing in PTCL with 6p25.3 rearrangements, and whether DUSP22 exerted tumor-suppressor properties." (PMID 27626696, 2016). "We then digested the tumor DNA with the methylation-sensitive HpaII restriction enzyme, thus fragmenting unmethylated DUSP22 alleles but not restriction-resistant methylated paralog alleles." (PMID 27626696, 2016). "The silencing of DUSP22 in PTCL with 6p25.3 rearrangements pointed out this gene as a candidate tumor suppressor whose inactivation may contribute to the pathogenesis of PTCL subtypes, notably ALCL (essentially cutaneous) and T-MF." (PMID 27626696, 2016).
tumor (continued). "Regardless of the partner (7q32.3, other or unknown), tested PTCL cases with monoallelic 6p25.3 alterations exhibited DUSP22 down-regulation, making it a candidate tumor-suppressor at this locus." (PMID 27626696, 2016). "However, the mechanism of second allele silencing and the putative tumor suppressor function of DUSP22 have not been investigated so far." (PMID 27626696, 2016). "In the present study, we showed that DUSP22 was significantly decreased in fatty liver of NASH individuals and in tumor tissues from NAFLD-HCC patients compared with the normal ones." (PMID 36209205, 2022). "Finally, we surprisingly found that DUSP22 reduced tumor size and number in DEN/HFHC-induced mouse model with NASH-related HCC, which was validated by the decreased HCC cell proliferation in vitro, indicating that DUSP22 may act as a tumor suppressor to further restrain NASH development into HCC." (PMID 36209205, 2022). "Dual specificity phosphatase 22 (DUSP22, also known as JKAP or JSP-1) expressed in numerous tissues plays essential biological functions in immune responses and tumor growth." (PMID 36209205, 2022). "The reduced expression of DUSP22 has been identified in TCL and this phosphatase likely behaves as a tumor suppressor gene in ALK- ALCL." (PMID 34572893, 2021). "DUSP22 gene knockdown reduced RCC invasion and the small molecule inhibitor BML-260 prevented RCC dissemination in a tumor/immune cell xenograft model." (PMID 34207247, 2021). "Given its tumor suppressive behavior in PTCL, DUSP22 is a candidate to be tested in tumors with 6p25 deletions, using a comprehensive approach such as described herein." (PMID 27626696, 2016). "FISH and quantitative SNP analysis of tumor and matching normal cells and DNA from these patients revealed that these tumors constitutionally lacked paralog sequences but did not exhibit DUSP22 deletions." (PMID 27626696, 2016). "However, lack of spontaneous tumorigenesis in Dusp22 knock-out mice clearly indicates that DUSP22 is not a gatekeeper tumor suppressor whose inactivation is sufficient to initiate tumor development." (PMID 27626696, 2016).
cancer (12 papers, 2017 to 2025). A tumor composed of atypical neoplastic, often pleomorphic cells that invade other tissues. "Methylation at three clusters (SPATC1L, VTRNA2-1, and DUSP22) showed significant associations with two types of cancer." (PMID 29310692, 2018). "Remarkably, at seven of these, peripheral blood DNA methylation at baseline was significantly associated with later cancer; three (SPATC1L, VTRNA2-1, and DUSP22) were significantly associated with multiple types of cancer." (PMID 29310692, 2018). "To investigate the impact of PD-L1 neutralization on HCC827 cancer cell migration heightened by DUSP22 deletion, we performed a cell migration assay with and without an anti-PD-L1 antibody (Atezolizumab)." (PMID 38877005, 2024). "On the other hand, inhibition of negative regulators such as PIAS3, SOCS1 and 3 and several cellular phosphatases (SHP1 and 2, PTPRD, PTPRT, PTPN1 and 2, DUSP22) can also lead to STAT3 activation in cancer." (PMID 35145111, 2022). "Although we used DUSP22 as a model to analyze phosphatase activity, the point is that many phosphatases, including DUSP22, exist in cancer cells." (PMID 36140125, 2022). "DUSP22 was shown to be a negative regulator for STAT3 in cancer cells, but its role in antiviral responses is undetermined." (PMID 28886690, 2017). "Dual specificity phosphatase 22 (DUSP22) is a pleiotropic signaling molecule that plays important roles in immunity and cancer." (PMID 40263624, 2025).
neurological diseases (2 papers, 2021 to 2022). "JNK pathway‐associated phosphatase (JKAP), also named as dual specificity protein phosphatase 22 (DUSP22), is reported to be involved in the regulation of immunity and inflammation; meanwhile, it is also implicated in the development and progression of neurological diseases." (PMID 34289265, 2021).
cardiovascular diseases (1 paper, 2024). "It would be useful to determine whether DUSP22 can regulate EndMT—this may lead to new therapeutic strategies for cardiovascular diseases such as cardiac hypertrophy, myofibrosis, cardiac remodeling, and heart failure." (PMID 38495810, 2024). "This line of reasoning led us to the hypothesis that DUSP22 may play a regulatory role in cardiovascular diseases through these signaling pathways." (PMID 38495810, 2024). "At present, there are no published reports focused on the role of DUSP22 in cardiovascular diseases." (PMID 38495810, 2024). "Thinking about the conclusion suggesting a role for DUSP22 in targeting strategies, we have not found studies of DUSP22 in cardiovascular clinical researches, so we cannot accurately conclude the relationship between DUSP22 in healthy people and patients with cardiovascular disease." (PMID 38495810, 2024). "However, there are no reports about the role of DUSP22 in cardiovascular diseases." (PMID 38495810, 2024).
infection (1 paper, 2025). The state of being infected such as from the introduction of a foreign agent such as serum, vaccine, antigenic substance or organism. "Besides MUC19, there are other interesting CNVs shown from our primary infection model, including IRF4/DUSP22 duplication and Notch homolog 2 N-terminal-like protein A (NOTCH2NLA) deletion." (PMID 40996224, 2025).
DUSP22 also shares sentences with these, for which no sentence is quoted: Sepsis (6 papers); experimental autoimmune encephalomyelitis (4); Crohn disease (3); Parkinson disease (3); Arthritis (2); breast carcinoma (2); depression (2); hyperlipidemia (2); Lymphomatoid Papulosis (2); Stroke (2); acute coronary syndrome (1); allergic disease (1); ankylosing spondylitis (1); atherosclerosis (1); chronic kidney disease (1); chronic obstructive pulmonary disease (1); Cognitive impairment (1); congenital heart defects (1); coronary heart disease (1); cutaneous T-cell lymphomas (1); cutaneous vasculitis (1); diabetic retinopathy (1); Down syndrome (1); Duane syndrome (1); eye movement disorder (1); gastrointestinal disease (1); hemorrhagic stroke (1); Hypertension (1); hyperuricemia (1); Hypoglycemia (1).
A further 17 diseases each share a sentence with DUSP22 in 1 paper.